TEX14 (testis expressed 14, intercellular bridge forming factor)
Description:
Required both for the formation of intercellular bridges during meiosis and for kinetochore-microtubule attachment during mitosis. Intercellular bridges are evolutionarily conserved structures that connect differentiating germ cells and are required for spermatogenesis and male fertility. Acts by promoting the conversion of midbodies into intercellular bridges via its interaction with CEP55: interaction with CEP55 inhibits the interaction between CEP55 and PDCD6IP/ALIX and TSG101, blocking cell abscission and leading to transform midbodies into intercellular bridges. Also plays a role during mitosis: recruited to kinetochores by PLK1 during early mitosis and regulates the maturation of the outer kinetochores and microtubule attachment. Has no protein kinase activity in vitro (By similarity).
Synonyms: SGK307; CT113; SPGF23
Tractability: Small molecule: it belongs to a druggable protein family. Antibody: the Human Protein Atlas places it where antibodies can reach.
Gene: Protein-coding gene on chromosome 17 (58,556,678 to 58,692,055, reverse strand). Ensembl gene ENSG00000121101.
Subcellular location: Cytoplasm; Midbody; Chromosome, centromere, kinetochore
Subcellular location (Human Protein Atlas): Cytosol; Plasma membrane; Vesicles
Gene Ontology:
Molecular function: protein binding; protein kinase binding; ATP binding; protein kinase activity
Biological process: attachment of spindle microtubules to kinetochore; intercellular bridge organization; male meiotic nuclear division; mitotic sister chromatid separation; mitotic spindle assembly checkpoint signaling
Cellular component: extracellular exosome; intercellular bridge; kinetochore; midbody; cytoplasm
Genetic constraint (gnomAD): Loss-of-function variants: 108 observed, 121.55 expected, observed/expected ratio (o/e) 0.89, 90% interval 0.76 to 1.04. The upper end of that interval is the gene's LOEUF score, 1.04, which puts it in group 4 of 6, group 1 being the genes least tolerant of losing a copy. Missense variants: 1,417 observed, 1,476.7 expected, observed/expected ratio (o/e) 0.96, 90% interval 0.92 to 1. Synonymous variants: 516 observed, 545.66 expected, observed/expected ratio (o/e) 0.95, 90% interval 0.88 to 1.02.
Homologues: Orthologues: chimpanzee TEX14 (99% identical), macaque TEX14 (94% identical), dog TEX14 (78% identical), pig TEX14 (75% identical), rabbit TEX14 (74% identical), rat Tex14 (68% identical), mouse Tex14 (66% identical), tropical clawed frog tex14 (27% identical).
Diseases named in the same sentence as TEX14 in open-access papers:
TEX14 is named in the same sentence as 19 diseases in open-access papers, as found by Europe PMC text mining. Sharing a sentence is not in itself a finding about the gene and the disease. The quoted sentences say what the papers report.
Infertility (8 papers, 2011 to 2025). "TEX14 also regulates intercellular bridges in the mouse ovary and mutations in Tex14 are associated with infertility in pigs and humans, consistent with a fundamental role for this protein in the regulation of stable intercellular bridges, at least in mammals." (PMID 36407108, 2022). "We previously reported that the lack of intercellular bridges in TEX14 null male mice results in the failure of spermatogenesis and infertility." (PMID 21364893, 2011).
cyst (4 papers, 2021 to 2026). A sac-like closed membranous structure that may be empty or contain fluid or amorphous material. "This behavior of Tex14 heterozygous cysts is one of several indications in our studies that intercellular bridges regulate cyst behavior, in addition to allowing materials to move between linked cells." (PMID 34156079, 2021). "This timing of TEX14 accumulation on intercellular bridges is also consistent with the timing of germ cell mitosis defects observed from E12.5 to E14.5 in homozygous mutant ovaries, where cyst formation takes place prior to TEX14-mediated bridge stabilization." (PMID 34156079, 2021). "Lineage-labeled clustered cyst germ cells were found in Tex14 homozygous mutant ovaries at a similar frequency as in wild-type gonads." (PMID 34156079, 2021). "In contrast, in Tex14 heterozygous mutant germ cells, reduced amounts of TEX14 protein leads to decreased cyst fragmentation and a slightly increased number of primary oocytes of reduced size." (PMID 34156079, 2021). "Our observations on the timing and localization of TEX14 protein in fetal ovaries suggests that TEX14 functions to stabilize bridges during mid to late cyst formation (E12.5-E14.5), instead of blocking cytokinesis." (PMID 34156079, 2021). "Instead, based on TEX14 labeling of intercellular bridges in spermatocyte cysts, we suggest that mouse meiotic cilia may have sensory roles affecting cyst function during prophase I." (PMID 36611937, 2022). "In summary, by characterizing the phenotypes of germ cell connectivity, germline cyst fragmentation, oocyte differentiation and folliculogenesis in Tex14 mutant mouse ovaries, we found additional evidence supporting the importance of development within cysts to oogenesis." (PMID 34156079, 2021). "To further characterize the mechanisms underlying defective intercellular bridge formation and altered germline cyst formation in Tex14 mutants, we stained E12.5 and E14.5 ovaries with a RacGAP antibody that labels early bridges and a TEX14 antibody that labels stable bridges." (PMID 34156079, 2021). "The fate of these large cysts contrasts with the expectation that only one cell per cyst can become an oocyte, Instead, heterozygous Tex14 cysts show a higher frequency of the oocyte formation (36.5%), but these primary oocytes contain less cytoplasm than wild type." (PMID 34156079, 2021). "By studying the effects of Tex14-induced cyst alterations in both heterozygous and homozygous mice, we also acquired new insights into the roles cysts play in oocyte differentiation, including how the number of primary oocytes and the cytoplasmic content of each oocyte may be determined." (PMID 34156079, 2021). "Applying single germ cell lineage tracing to Tex14 mutant ovaries showed that the fertility of Tex14-/- animals is not due to oocyte production in the absence of cysts but because cyst production continues in the absence of stable IBs." (PMID 36445738, 2022). "During early cyst formation from E10.5 to E12.5, about half of the RacGAP-positive intercellular bridges were TEX14 negative." (PMID 34156079, 2021). "Cytoplasmic transfer did not require normal intercellular bridges in Tex14 homozygous mutant ovaries, but took place with near wild type efficiency even when cyst structure was severely perturbed." (PMID 34156079, 2021). "However, the fertile phenotype in the Tex14 knockout mouse model, in which females lacked IBs, suggested that the cyst structure might not be indispensable for oocyte fate determination and the cyst-dependent germ cell model might not be the only mechanism for the oocyte selection in mice." (PMID 41361694, 2026).
atherosclerosis (2 papers, 2022 to 2024). A disease characterized by the build-up of fatty material and calcium deposition in the arterial wall resulting in partial or complete occlusion of the arterial lumen. "Research shows that rs651007 and rs411988 (TEX14, LOC105371842 gene) affect ferritin concentration, and the former also reduces the risk of atherosclerosis." (PMID 38474722, 2024).
Azoospermia (2 papers, 2018 to 2021). Absence of any measurable level of sperm,whereby spermatozoa cannot be observed even after centrifugation of the semen pellet. "Another group of authors managed to identify three novel causative mutations of azoospermia in three genes: MIO, TEX14, and DNAH6 in brothers from three families." (PMID 34178030, 2021). "Therefore, this study aimed to replicate this finding in humans byexamining the expression levels of TEX11, TEX12,TEX14, and TEX15 in the testis tissue of patients withnon-obstructive azoospermia and comparing them against controls." (PMID 29932616, 2018).
breast carcinoma (2 papers, 2013 to 2024). "TEX14 has been implicated in multiple myeloma and breast cancer, and INSRR has been implicated in ovarian epithelial cancers and neuroblastomas." (PMID 23826350, 2013). "As for TEX14, a factor necessary for intracellular bridges in germ cells, it marked luminal B breast cancers, as well as luminal A tumors to a smaller extent." (PMID 38467851, 2024).
triple-negative breast carcinoma (2 papers, 2017 to 2024). An invasive breast carcinoma which is negative for expression of estrogen receptor (ER), progesterone receptor (PR), and human epidermal growth factor receptor 2 (HER2). "The upregulation of TEX14 in SNMM may affect the degradation of the REST tumor suppressor, a protein associated with adverse outcomes in cancers such as triple-negative breast cancer, potentially driving the aggressive phenotype of SNMM through disrupted cell cycle regulation." (PMID 39766071, 2024). "Our studies, however, do not contest the possible role of Tex14 in mediating REST turnover; the formation of an STP complex; or the possibility of SCYL1, Tex14, PLK1, and REST being aberrantly expressed in triple-negative breast cancer cells." (PMID 28570664, 2017).
Germ Cell Tumours (1 paper, 2018). "TEX14 is found in a locus that contributes to the susceptibility for Testicular Germ Cell Tumours and it will be important to determine whether control of ESCRT-dependent abscission affects the development of germ cell tumours." (PMID 28843980, 2018).
male infertility (1 paper, 2011). The inability of the male to effect fertilization of an ovum after a specified period of unprotected intercourse. "Thus, Tex14 knockout mice completely lack intercellular bridges, and spermatogenesis fails before the first meiotic division resulting in male infertility." (PMID 22136159, 2011).
seminoma (1 paper, 2025). A radiosensitive malignant germ cell tumor found in the testis (especially undescended), and extragonadal sites (anterior mediastinum and pineal gland). "The TGCT susceptibility genes TEX14, NARS2, and G3BP2, were identified as hub genes in both seminoma and non-seminoma networks." (PMID 39809819, 2025).
sterility (1 paper, 2022). "Five genes (Tsga10, Terb1, Stra8, Tex14, and Spam1) were predicted to be associated with sterility in male and female Mule ducks." (PMID 36386800, 2022).
tumor (4 papers, 2020 to 2024). "For TEX14, this result is consistent with the heterogeneous expression patterns observed in tumors, where the tumor microenvironment also expresses this C/T gene." (PMID 38467851, 2024). "Finally, the expression pattern for the ER-related markers was more precarious, showing only a minority of tumor cells expressing either TEX14 or LRGUK, with a significant contribution of cells from the microenvironment for TEX14 expression." (PMID 38467851, 2024).
cancer (3 papers, 2024 to 2025). A tumor composed of atypical neoplastic, often pleomorphic cells that invade other tissues. "Similarly, testis-restricted targets such as SPA17, TEX14, LAMA1, SMOC1, TNFAIP6, GPC2, and COL20A1 may also be leveraged for their cancer-specificity." (PMID 38702309, 2024).
TEX14 also shares sentences with these, for which no sentence is quoted: breast tumors (1 paper); female sterility (1); infection (1); multiple myeloma (1); neuroblastoma (1); ovarian carcinoma (1); premature ovarian failure (1).